ABCG2 (ATP binding cassette subfamily G member 2 (JR blood group))
Diseases named in the same sentence as ABCG2 in open-access papers (continued):
Sharing a sentence is not in itself a finding about the gene and the disease.
cancer (continued). "Single nucleotide polymorphism of ABCG2 has been detected in various cancer cells and may contribute to a degree of resistance against chemotherapeutic drugs." (PMID 32957726, 2020). "Except CD44+CD133+ subset and OV6+ subset, we found that HBx upregulated a subset with positive expression of ABCG2, a drug resistance-associated protein, which had been characterized by high expression of cancer stemness-related proteins, including Oct4, Bmi-1, and CD44." (PMID 32168902, 2020). "Long-term treatment with chemotherapeutic agents may lead to an increase in the expression of ABCG2 in cancer cells, causing an increase in the efflux and decrease in the intracellular accumulation of its substrates, thereby causing MDR." (PMID 32899268, 2020). "As irinotecan is reported as a substrate of ABCG2, exposing cancer cells to irinotecan may cause an up-regulation of both ABCG2 mRNA and protein expression level." (PMID 33692943, 2020). "ABCG2 promotes the extracellular efflux of various carcinogens, including 2-amino-1-methyl-6-phenylimidazo [4, 5-b] pyridine, so the risk of cancer may be increased by intracellular accumulation of carcinogens if ABCG2 activity is inhibited." (PMID 31340525, 2019). "The ABCG2 membrane protein is a key xeno- and endobiotic transporter, modulating the absorption and metabolism of pharmacological agents and causing multidrug resistance in cancer." (PMID 29749379, 2018). "To identify the mechanisms underlying the promoting effect of fructose substitution on cancer metastasis, we performed RNA-seq analysis to analyze ABCG2-positive subpopulations and unsorted parent PANC-1 cells cultured under glucose-containing or fructose-substituted conditions for 4 weeks." (PMID 28032597, 2017). "We also found that 17% of carcinoma cases had gene mutations in ABCG2 C421A loci." (PMID 29340035, 2017). "Clearly, these structural data may provide important clues to decipher the effects of the ABCG2 variants, design drugs to rescue their expression, or drugs to modulate their function in stem cell development, protection of the fetus or cancer drug resistance." (PMID 27741279, 2016). "ABCG2 has also been linked to cancer cells that exhibit stem-like properties." (PMID 26714461, 2015). "ABCG2 has been linked to treatment failure and decreased survival in a number of different cancers." (PMID 26714461, 2015). "ABCG2/BCRP increases the efflux of these TKIs from cancer cells, therefore causing resistance." (PMID 25191874, 2014). "Notably, a case-controlled study of Japanese cancer patients indicated that rs2622604, an SNP in an intron in ABCG2, increased the risk of severe myelosuppression due to CPT-11 treatment." (PMID 24932285, 2014). "Consistent with the hypothesis that aberrant miRNA expression can cause cancer drug resistance, low miR-328 expression was found to correlate with the overexpression of ABCG2 in resistant MCF-7/MX100 breast cancer cells." (PMID 24358977, 2013). "However, the studies published by Hu and Korenaga were contradictory to ours, indicating that carriers of the A allele of ABCG2 C421A had an increased risk of cancer." (PMID 22937733, 2012). "Moreover, growing evidence suggests that ABCG2 underlies the MDR of clinical samples from different cancers." (PMID 22778999, 2012). "Therefore, in order to gain insights into the association between polymorphism of ABCG2 C421A and cancer risk, we conducted a meta-analysis of eligible case–control and cohort studies." (PMID 22937733, 2012). "Furthermore, these authors also performed a meta-analysis of 3 studies, which provided evidence of a significant association between decreased cancer risk and the ABCG2 C421A polymorphism." (PMID 22937733, 2012). "The association between ABCG2 and cancer has been extensively studied." (PMID 23153066, 2012). "We found that the ABCG2 C421A polymorphism is a protective factor for developing cancer." (PMID 22937733, 2012).
cancer (continued). "Recently, a number of studies have investigated the relationship between the C421A polymorphism in ABCG2 and cancer risk in multiple populations and various types of cancers; however, this relationship remains unclear." (PMID 22937733, 2012). "Since patients have demonstrated individual differences in their response to photodynamic therapy, transcriptional activation and/or genetic polymorphisms of the ABCG2 gene in cancer cells may affect patients' responses to photodynamic therapy." (PMID 21188243, 2010). "The intracellular concentration of MTX-211 in S1-MI-80 cancer cells (5.92 ± 0.69 pmoles/μL) was notably lower than that in the parental S1 cancer cells (19.9 ± 0.95 pmoles/μL), a phenomenon that was susceptible to restoration by blocking the function of ABCG2 with Ko143." (PMID 38791198, 2024). "In addition, ABCG2 overexpression in various cancers causes anticancer drug resistance." (PMID 37887994, 2023). "However, it remains unclear, which of the ABCG2 mutation sites are found in different types of cancers and how it might influence the drug–ABCG2 interactions." (PMID 36555598, 2022). "Consequently, ABCB1 and ABCG2 are often associated with the development of multidrug resistance (MDR) in human cancer cells that could result in relapse and treatment failure in cancer patients." (PMID 33807514, 2021). "However, CSCs and hypoxia-adapted cancer cells may be less susceptible to small-molecule radiosensitizers due to the overexpression and high activity of membrane transporters ABCG2, ABCB1 and others that pump drugs out of the target cell." (PMID 33806538, 2021). "Thus, OTS964 is an MDR-susceptible agent due to its interactions with ABCG2, and overexpression of ABCG2 transporter may attenuate its therapeutic effect in cancer cells." (PMID 33658942, 2021). "Additionally, GC patients with high GLI1/GLI2 and ABCG2 signatures were associated with a shorter overall survival (OS) and higher cancer relapse, suggesting that higher expressions of these genes predicted a poorer outcome in GC patients who underwent 5-FU and cisplatin-based chemotherapy." (PMID 34638233, 2021). "Moreover, we discovered that sitravatinib could be repositioned into an effective modulator of both ABCB1 and ABCG2 to combat against multidrug resistance associated with the overexpression of ABCB1 or ABCG2 in human cancer cells." (PMID 31941029, 2020). "Moreover, ABCG2 is a potential target causing the multidrug resistance in NSCLC; suppression of ABCG2 transcription, as shown in A549 cell-based models, may reverse the multidrug resistance and thus enhance the effectiveness of other anti-cancer drugs." (PMID 26967245, 2016). "Therefore, ABCG2 SNPs alter the expression and transporter activity of ABCG2 protein and thus may be associated with the development of carcinoma and interindividual variability in drug response to anticancer agents and the clinical outcome." (PMID 26634205, 2015). "To date, there have been a great deal of epidemiological studies to investigate the association between the C421 polymorphism in ABCG2 and the risk of various types of cancers, however, the exact relationship between cancer susceptibility and the ABCG2 C421A polymorphism remains unclear." (PMID 22937733, 2012). "The studies presented here serve to underscore the importance of amino-acid 482 in defining the substrate specificity of the ABCG2 protein and raise the possibility that amino-acid 482 mutations in human cancers could affect the clinical application of antagonists for ABCG2." (PMID 14612912, 2003). "CD147 is recognized as a multifaceted driver of cancer progression, chemoresistance by affecting hyaluronan production, lactate efflux, and subcellular localization of ABCG2 23, and stemness via fucosylation." (PMID 41362734, 2026). "A significantly positive correlation was found between p38/MAPK14 and ABCG2 in these five carcinomas." (PMID 41541684, 2026).
cancer (continued). "KSQ‐4279 was shown to significantly elevate the antitumor function of multiple conventional chemotherapeutic drugs in MDR cancer cell lines driven by ABCB1/ABCG2/ABCC1 overexpression in vitro independently on its own cytotoxicity." (PMID 41328326, 2025). "By using various in vitro cellular and membrane vesicular assays, we have shown that some of the primaquine fumardiamides have potent inhibitory effects on ABCG2 and can sensitize cancer cell lines to the chemotherapeutic agent mitoxantrone." (PMID 40508176, 2025). "COX-2, ABCB1, and ABCG2 overexpression are typically correlated in cancer, contributing to chemotherapy resistance." (PMID 40253988, 2025). "The results demonstrated that tinodasertib effectively counteracts ABCG2-mediated MDR in various cancer cell lines and HEK293 cells expressing different ABCG2 variants." (PMID 40584625, 2025). "This senescent phenotype is linked to chemotherapy resistance and cancer recurrence via multidrug resistance mutation 1 (MDR1) and ATP binding cassette subfamily G member 2 (ABCG2)." (PMID 40572053, 2025). "ABCG2 is highly expressed in several drug-resistant cancer cells, where it actively effluxes chemotherapeutic agents, such as mitoxantrone, topotecan, and anthracyclines, thereby reducing their intracellular accumulation and limiting their cytotoxic effects." (PMID 41471102, 2025). "ABCG2 consistently displayed the lowest level of genetic alterations in both cancers, suggesting a potential role in maintaining cellular homeostasis." (PMID 40641097, 2025). "ABCG2 is another gene affected by MPs, and it encodes Breast Cancer Resistance Protein (BCRP), another ABC transporter involved in MDR by exporting chemotherapeutic agents, such as mitoxantrone and doxorubicin, out of cancer cells, reducing drug efficacy." (PMID 41378310, 2025). "We found that single-cell analysis (GSE138709) revealed that ABCG2 expression in specific cells, such as endothelial or malignant tumor cells, was increased compared to the normal group." (PMID 40282409, 2025). "ABCG2 is a transporter protein that pumps out drug compounds, interfering with the effectiveness of drugs during cancer treatment and preventive therapy." (PMID 40363725, 2025). "Downregulated expression of ABCG2 in normal and cancer tissues from colectomy specimens was confirmed in CRC." (PMID 41465541, 2025). "Research has shown that ABCG2 is upregulated in various cancer cell lines with drug resistance, including gastric, breast, colon, lung, and ovarian cancers that exhibit drug resistance." (PMID 39931465, 2025). "Single-cell RNA sequencing based on GSE138709 revealed elevated ABCG2 expression in endothelial cells of cancer patients compared to normal tissues." (PMID 40282409, 2025). "Similar considerations regarding a potential use for combating multidrug-resistant cancer were made for tazemetostat, a triple inhibitor of ABCB1, ABCC1 (multidrug resistance-associated protein 1, MRP1) and ABCG2." (PMID 40284428, 2025). "The multidrug resistance-associated gene ABC transporter ABCG2 can form a complex with SLC1A5 in MCF-7 cells to facilitate glutamine influx and enhance redox regulation, providing a survival advantage to cancer cells under oxidative stress." (PMID 39973065, 2025). "• ABCG2-siRNA-loaded NP with UTMD effectively silenced the ABCG2 gene and enhanced ADR susceptibility in MCF-7/ADR (ADR-resistant human cancer cells)." (PMID 41426324, 2025). "ABCG2, an ATP-binding cassette transporter, shows consistently low expression across most cancers, including SCTs, suggesting a common mechanism of downregulation during carcinogenesis." (PMID 41439026, 2025). "ABCG2 functions as a drug efflux pump, contributing to multidrug resistance by expelling chemotherapy agents from cancer cells." (PMID 39931465, 2025). "These structural features contribute to the high affinity and selectivity of inhibitor 7b for ABCG2, making it a promising candidate for overcoming multidrug resistance in cancer therapy." (PMID 41471102, 2025).
cancer (continued). "For instance, the dysregulation of a member of the ABC transporter family, known as ABCG2, has emerged as a prominent factor mediating chemoresistance in various cancers." (PMID 40282556, 2025). "Inhibiting the ABCB1 or ABCG2 transport proteins can abolish chemoresistance and increase the death of chemoresistant cancer stem cells." (PMID 40943558, 2025). "BCRP/ABCG2 is a membrane-bound multidrug transporter often overexpressed in cancer cells, contributing to their resistance to conventional treatments." (PMID 41226696, 2025). "ABCG2 actively pumps chemotherapeutic agents out of cancer cells, reducing their intracellular concentrations and diminishing their cytotoxic efficacy." (PMID 40584625, 2025). "The ATP-binding cassette transporter ABCG2 plays a critical role in drug pharmacokinetics and multidrug resistance in cancer therapy." (PMID 40806557, 2025). "Given the pump‐like function of ABC transporters, the impact of KSQ‐4279 on ABCB1‐, ABCG2‐, and ABCC1‐caused doxorubicin efflux was further evaluated by quantifying the change of doxorubicin inside cancer cells over time." (PMID 41328326, 2025). "Knockdown of linc-VLDLR reduces the level of ABCG2 drug efflux transporters and decreases cancer cell proliferation." (PMID 40352931, 2025). "Combining tinodasertib with drugs that serve as substrates for ABCG2 presents a promising approach to tackling MDR in cancer treatment." (PMID 40584625, 2025). "Next, EMT is associated with an increased expression of ABC transporters (e.g., ABCB1, ABCG2), which pump chemotherapeutic agents out of the cancer cells." (PMID 41154409, 2025). "Given the pivotal role of ABCG2 in protecting cancer cells from chemotherapeutic agents by actively exporting drugs, the ability of tinodasertib to inhibit this process suggests a promising strategy to sensitize drug-resistant cells to therapy." (PMID 40584625, 2025). "The dual-gold complex QB1561 partially reversed MDR mediated by ABCG2 and effectively suppressed the proliferation of drug-resistant cancer cells overexpressing ABCB1 and ABCG2." (PMID 40066335, 2025). "In consistency with these findings, axitinib reversed ABCG2-mediated MDR in cancer cells in vitro by enhancing the cytotoxicity of topotecan and mitoxantrone in human lung cancer cell lines." (PMID 41154409, 2025). "The key transporter that actively removes TOP from cancer cells is the breast cancer resistance protein (BCRP), encoded by the ABCG2 gene." (PMID 40565261, 2025). "This work offers valuable mechanistic insights into the structural dynamics of ABCG2, paving the way for novel drug development strategies to combat anti-cancer resistance." (PMID 40165990, 2025). "We also found that FOXP1 directly modulated the expression of ABCG2, a membrane transporter that promotes the efflux of gemcitabine from cancer cells." (PMID 40169859, 2025). "RN486, a Bruton’s tyrosine kinase (BTK) inhibitor, has been shown to antagonize ABCG2-mediated resistance in preclinical models, enhancing drug retention in ABCG2-overexpressing cancer cells." (PMID 40547482, 2025). "The breast cancer resistance protein (BCRP/ABCG2) plays a major role in the multidrug resistance of cancers toward chemotherapeutic treatments." (PMID 39835420, 2025). "KSQ‐4279, an USP1 inhibitor in clinical trial, widely reversed multidrug resistance in refractory cancers by competing for the drug‐binding pockets of ABCB1/ABCG2/ABCC1 and blocking chemotherapeutic drugs’ efflux." (PMID 41328326, 2025). "This interaction highlights a possible mechanism by which tinodasertib inhibits ABCG2-mediated drug efflux, further supporting its role as an effective reversal agent for multidrug resistance in cancer therapy." (PMID 40584625, 2025). "Nrf2 and Wnt/β-catenin signaling have been demonstrated to increase transcript and protein levels of multiple ABC transporter protein (including P-gp, MRP1 and ABCG2) and confer chemoresistance phenotype in various cancers." (PMID 40612109, 2025).
cancer (continued). "Key examples include P‐glycoprotein (P‐gp/ABCB1), multidrug resistance (MDR)‐associated protein 1 (MRP1/ABCC1), and breast cancer resistance protein (BCRP/ABCG2), all of which have been extensively studied in various cancers, including OS." (PMID 39844613, 2025). "ABCG2 acts as a multidrug resistance transporter by expelling chemotherapeutics from cancer cells, while MDR1, an ATP‐dependent transporter, plays a similar role in detoxification and resistance." (PMID 40572053, 2025). "A significant correlation between pathological cancer stages and ABCG2 expression was shown; its expression was higher in stage 4 in comparison with stage 3 of LUSC." (PMID 39457707, 2024). "The binding sites of ABCB1, ABCC1 and ABCG2 are highly flexible and known to bind and transport diverse compounds including anti-cancer drugs." (PMID 38766631, 2024). "ABCG2 has been identified not only in cancer cells but also in various types of normal tissues, including the endothelial cells lining blood vessels." (PMID 38542090, 2024). "Known stromal EMT-inducing signals, such as hypoxia, inflammation, and TGF-beta, enhance the expression of key ABC transporters, including ABCB1 (P-gp), ABCC1 (MRP1), and ABCG2 (BCRP), in various cancers, including PDAC." (PMID 39114357, 2024). "Studies in cancer cell lines prove that NF-kB directly binds the ABCG2 promoter, enhancing BCG2 expression and membrane translocation of the protein." (PMID 38255216, 2024). "Overcoming ATP-binding cassette subfamily G member 2 (ABCG2)-mediated multidrug resistance (MDR) has attracted the attention of scientists because one of the critical factors resulting in MDR in cancer is the overexpression of ABCG2." (PMID 39081282, 2024). "ABCG2+ cells are progenitor cells with multi-directional differentiation potential, and ABCG2- cells contain primitive stem cell-like cancer cells." (PMID 39668824, 2024). "Crucially, this effect was mediated by miR‐99a‐5p’s suppression of ABCG2, leading to significant doxorubicin accumulation and enhanced cytotoxicity in cancer cells." (PMID 39679367, 2024). "The primary tumor environment differs from that of distant metastases, and cells originating from these different stages of cancer progression show different expression patterns of markers such as ABCG2 and ALDH1." (PMID 38787133, 2024). "ABCG2’s role is widely known for conferring multidrug resistance in cancer, acting as an efflux pump for anti-cancer medications, such as methotrexate, topotecan, and mitoxantrone." (PMID 38442133, 2024). "Through the utilization of energy sourced from ATP hydrolysis, ABCG2 actively expels a diverse array of therapeutic drugs from cancer cells, diverting them away from their intracellular targets." (PMID 38791198, 2024). "This study demonstrates the potential of ABCG2 gene expression as well as its methylation evaluation as a biomarker in cancer through in silico and wet analyses." (PMID 39457707, 2024). "ABCC2 (MRP2) and ABCG2 (BCRP) are among the most important drug transporters that determine the pharmacokinetics of many drugs and whose overexpression is associated with cancer chemoresistance." (PMID 38612927, 2024). "As ABCG2 was demonstrated in multidrug-resistant cancer cell lines, the first identified protein substrates were chemotherapeutic agents such as mitoxantrone, flavopiridol, methotrexate, irinotecan, and its active metabolite SN-38." (PMID 38255216, 2024). "ABC transporters such as P-glycoprotein (ABCB1) and breast cancer resistance protein (ABCG2) actively extrude chemotherapeutic agents like Tx from cancer cells, thereby reducing their intracellular concentrations and contributing to resistance." (PMID 38914845, 2024). "Another transporter most often described in the context of multidrug resistance in cancer cells is ABCG2." (PMID 39175042, 2024). "Small-molecule inhibitors and monoclonal antibodies against ABCG2 were shown to effectively sensitize resistant cancer cells to chemotherapy." (PMID 38542090, 2024).